FAM87A (family with sequence similarity 87 member A)
Gene: Long non-coding RNA gene on chromosome 8 (375,931 to 384,079, reverse strand). Ensembl gene ENSG00000182366.
Subcellular location: Membrane
Diseases named in the same sentence as FAM87A in open-access papers:
FAM87A is named in the same sentence as 4 diseases in open-access papers, as found by Europe PMC text mining. Sharing a sentence is not in itself a finding about the gene and the disease. The quoted sentences say what the papers report.
colon cancer (1 paper, 2022). "Finally, we further studied the functions and mechanisms of DNMBP-AS1 and FAM87A in colon cancer to find effective therapeutic targets for CC patients." (PMID 35574307, 2022). "The results of 30 pairs of human colon cancer tissues and their adjacent normal tissues showed that DNMBP-AS1 and FAM87A expression were elevated in normal tissues." (PMID 35574307, 2022).
gastric cancer (1 paper, 2024). A primary or metastatic malignant neoplasm involving the stomach. "Transwell assays showed that FAM87A knockdown inhibited the migration and invasion abilities of gastric cancer cells in vitro." (PMID 39386192, 2024). "RT-qPCR experiments showed that FAM87A expression was upregulated in gastric cancer tissues compared to normal samples (n = 30)." (PMID 39386192, 2024). "FAM87A could be a potential biomarker for the overall survival of patients with gastric cancer." (PMID 39386192, 2024).
tongue squamous cell carcinoma (1 paper, 2022). A squamous cell carcinoma that arises from the tongue. "FAM87A (also known as family with sequence similarity 87 member A) could regulate the progression of tongue squamous cell carcinoma (TSCC) through ceRNA network, and high expression of FAM87A is associated with poor prognosis of TSCC patients." (PMID 35574307, 2022).
FAM87A also shares sentences with these, for which no sentence is quoted: glioma (1 paper).